FAS (Fas cell surface death receptor)
Diseases named in the same sentence as FAS in open-access papers (continued):
Sharing a sentence is not in itself a finding about the gene and the disease.
cancer (continued). "Interestingly, human adipose tissue macrophages resemble human tumor-associated macrophages and increase the expression of FAS in cancer cells, thus playing a critical role in cancer cell survival." (PMID 24073332, 2013). "The reduced influence for cancer risk was lower than FAS -1377 G/A polymorphism alone." (PMID 24014103, 2013). "However, the complete loss of FAS expression is hardly observed in human cancer." (PMID 35249111, 2022). "Promoter polymorphisms FAS-670 A>G and FAS-844 T>C which alter the transcriptional activity of these genes may grant a risk to develop cancer and revamp the drug activities towards the cancer cell." (PMID 33639675, 2021). "Interestingly, our panel included genes already described to be cancer predisposition genes (FAS, ITK, KIF1B, PGR and MET) or previously reported as playing important roles in cancer (ABI1, ARID5B, DNMT3A, HEY1, KDM5C, NCOA1, NUP98, and SLC34A2), or in DNA repair process (FANCF)." (PMID 30925779, 2019). "As a result, targeting the FAS pathway is emerging as a promising therapeutic strategy for cancer treatment." (PMID 41188939, 2025). "The largest number of disease/pathway links was found for the apoptosis-mediating FAS (n = 52) and for two cancer-related proteins, EGFR (n = 43) and ERBB2 (n = 39)." (PMID 40593564, 2025). "Previous studies have suggested that cannabidiol (CBD), a crucial immune checkpoint receptor in cancer cells, can regulate FAS expression." (PMID 41188939, 2025). "Unexpectedly, some cancer cells depend on the constitutive activity of FAS, stimulated by cancer-produced FASLG, for optimal growth." (PMID 39068622, 2024). "FAS was positive in only 37.5% of cancers, while FAS was expressed in 87.5% of surrounding peritumoral urothelium and in normal bladder tissue." (PMID 38791085, 2024). "The majority of studies, however, highlight the possible link between cancer and gradual FAS—and sometimes also FASL—overexpression." (PMID 37382757, 2024). "For both platforms, gene expression of FAS was found to be significantly altered in several cancer types." (PMID 39416461, 2024). "Cytotoxic CD8+ T cells are crucial in maintaining anti-cancer immunity through their direct targeting of cancer cells via FAS-mediated apoptosis and perforin-mediated cytolysis." (PMID 38730579, 2024). "DR4 and FAS showed inverse correlation to cancer-specific death (p = 0.002, and p = 0.001, respectively)." (PMID 38791085, 2024). "Our analysis revealed that elevated PLEK2 expression was significantly associated with increased expression of several key immune checkpoint molecules, such as CD276 (B7-H3), CD274 (PD-L1), LGALS9, PVR (CD155), and FAS across a wide spectrum of cancers." (PMID 39546161, 2024). "In numerous types of cancers, the expression of immune sensors, such as MICA, FAS, MHC-I, CD155, ULBP 2/5/6, are down-regulated, which causes disorders in the recognition of cancer cells by immune cells." (PMID 38589867, 2024). "Mechanisms to elude apoptosis devised by cancer cells include altered expression of FAS and its ligand FAS-L, which can activate apoptosis signaling and induce cell death." (PMID 38891056, 2024). "The DR TRAIL-R1/2 and CD95 (also known as FAS) contribute to the immunosurveillance towards cancer or infected cells by their ability to induce cell death upon engagement by their ligand, TRAIL and CD95L, respectively." (PMID 38383861, 2024). "In principle, our method of sensitization of cancer cells to FAS agonists creates an opportunity to use them at lower doses." (PMID 39068622, 2024). "Through this axis, overexpressed PIR inhibits NFκB2 transcriptional activity toward FAS and therefore assists cancer cells surviving from FAS‐dependent insults, especially from immune defense system." (PMID 38148593, 2024).
cancer (continued). "The expression levels of FASLG and FADD in almost all cancer types were higher than those in normal tissues, and FAS was downregulated in most types of cancer." (PMID 36583248, 2023). "AIM2, ZBP1, STAT1, and FAS mediate the immune response and play important roles in a variety of diseases, cancers, and infections." (PMID 37205113, 2023). "The interaction of FASL and its cell surface receptor, FAS, triggers apoptosis in normal cells; however, this function is altered in cancer cells." (PMID 37569529, 2023). "We also observed that demethylation of the FAS promoter led to an increase in expression, which suggests the possibility of using demethylating agents such as decitabine to increase cell surface FAS expression in cancer cells." (PMID 37569529, 2023). "In agreement with our simulations, simultaneous inhibition of the ACL and FAS genes hindered cancer cell division." (PMID 36677837, 2023). "Treatment of BBC and GBM cancer cells with AS1842856 led to increases in FAS (FAS cell surface death receptor) and BIM (BCL2L11) gene expression, as well as increased positivity for markers for apoptosis such as annexin V and propidium iodide." (PMID 36602390, 2023). "FAS-mediated apoptosis is another crucial mechanism of apoptosis, which is directly dependent on antigen-presenting cell interaction with cancer cells." (PMID 37415974, 2023). "It is interesting to note that both API and miR-155 have common apoptotic targets in cancer cells such as caspase 3, caspase 9, FAS and Bcl2." (PMID 35892872, 2022). "Unexpectedly, FAS knockout suppressed the phosphorylation of cancer cell survival signaling molecules, such as AKT-S473, ERK1/2-T202/Y204, ERK1/2-T185/Y187, and AMPKα1-T174." (PMID 35249111, 2022). "Tumoral FAS expression alone is sufficient to predict the survival of CAR-T-treated human cancer patients." (PMID 35053524, 2022). "Overexpression of FAS is related to the development of cancer, as this enzyme is involved in fatty acid biosynthesis." (PMID 35967759, 2022). "FAS knockout inhibited in vitro cancer spheroid formation, migration and invasion, and prevented mesenchymal transition in OSCC cells and inhibited OSCC pulmonary metastasis in vivo." (PMID 35249111, 2022). "Cytotoxic CD8+ T cells play a major role in sustaining anti-cancer immunity by attacking cancer cells directly (through FAS-mediated apoptosis and perforin-mediated cytolysis)." (PMID 35634289, 2022). "When activated by its ligand (FASL), FAS induces apoptosis, and can therefore be considered a marker of cell apoptosis, including that of cancer cells." (PMID 35682983, 2022). "It seems that cancer cells can release microvesicles with FAS and TRAIL, which, instead, induce apoptosis of cancer cells and target and eliminate CTLs as an immune escape mechanism." (PMID 34371753, 2021). "Here we show that the activities of perforin/granzyme B and FAS/FASL pathway both participates in the cancer cell lysis by V-aCD3 in vitro." (PMID 33824272, 2021). "FAS and FASLG genes have a crucial role in apoptosis processes and their polymorphisms have been reported to affect the risk of cancer, including SPCs." (PMID 34078296, 2021). "Reinforcing this view, knockdown of E2F2 in a different experimental setting (a cancer-derived human cell line) leads to FAS promoter activation and transcription." (PMID 35008734, 2021). "In cancer, it has been shown that hypoxia can induce FAS expression, possibly via sterol regulatory element-binding protein 1c (SREBP1c)." (PMID 34055796, 2021). "The most well-established activity of affected proteins in the FAS–FAS ligand and Caspase pathway is to mediate the apoptotic death of either virus-infected cells or cancer cells when engaged by a cytotoxic lymphocyte." (PMID 34484227, 2021). "HIPK3, a FAS/FADD-interacting kinase downregulated in our study, has been previously implicated in multidrug resistance in cancer." (PMID 32260415, 2020).
cancer (continued). "High expression of FAS is correlated with molecular changes in various types of cancer cells including breast cancer." (PMID 32099006, 2020). "Several studies have reported that FAS expression was downregulated in various cancers, including lung cancer." (PMID 32963220, 2020). "Since both FAS and IL6 were closely associated with cancer pathogenesis and STAT3 activation, we investigated IL6 mRNA and protein levels after FAS knockdown." (PMID 32963220, 2020). "In summary, FAS has a dual and complicated role in tumors, including both anti-cancer and cancer promotion functions." (PMID 31942177, 2020). "The results of this study showed that HI NK cells, in particular the CD56bright subset, had strong cytotoxicity against certain HCC cell lines which expressed NKG2D ligands and FAS, supporting potential cancer immunotherapy using HI NK cells." (PMID 30925759, 2019). "Beside FAS-L/FAS, the interaction of PD-L1 of cancer cells with the PD1 receptor on the surface of CD8+ T-lymphocytes is a critical reaction of the immune checkpoint resulting in functional loss of anti-cancer activity of CD8+ T-lymphocytes." (PMID 30783513, 2019). "The present study also shows higher expression levelof CD95 (FAS) on the studied cancer cells after treatmentwith Plts or Plt-derived components." (PMID 29308628, 2018). "RNA-seq found that knockdown of HOXC-AS3 affected key cancer-related genes, such as p21, FAS, and CCND1." (PMID 30286788, 2018). "Among these abnormalities, from a cDNA array, we first focused on FAS as a gene generally considered strongly affect the biology of cancer cells." (PMID 29563856, 2018). "In this review, aberrant splicing events in cancer-associated genes, namely BCL2L1, FAS, HRAS, CD44, Cyclin D1, CASP2, TMPRSS2-ERG, FGFR2, VEGF, AR and KLF6, will be discussed." (PMID 30463359, 2018). "In this study, we found for the first time that CD95/FAS is a pivotal target that induces cancer cell apoptosis in response to plasma treatment." (PMID 29719586, 2018). "SSC demonstrated functional activity in 100% of cancer patients and healthy volunteers; which was significantly higher than those for FAS and CAT." (PMID 28935966, 2017). "In hormone-dependent cancer cells, the FAS/ FASL complex translocates to the cell membrane, and the death inducing signaling complex (DISC) forms, resulting in activation of the caspase cascade effect." (PMID 27340675, 2016). "What's more, PD-L1 acts not only as a ligand of PD-1, but can also serve as a receptor transmitting reverse signals that protect cancers cells from apoptosis mediated by FAS-FASL pathway." (PMID 26930715, 2016). "The extrinsic pathway is triggered in cancer cells by the stimulation of apoptotic membrane receptors like FAS and TRAIL-R which lead to CASPASE8 activation and, in turn CASPASE3 cleavage." (PMID 26843614, 2016). "FAS is a critical component of the FAS-mediated apoptosis pathway and thus an attractive target in cancer therapy." (PMID 25605245, 2015). "Despite many investigations, the associations between DR4, FAS, and FASL polymorphisms and the risk of human cancers remain inconsistent between different studies." (PMID 24587306, 2014). "Aiming to elucidate this ontological question of cancer etiology, we began to investigate the effects of the dysregulation of FAS/FASL in notochord during embryo development." (PMID 25071022, 2014).
cancer (continued). "In the present study, FAS expression was examined in patients with gastric cancer by immunohistochemical staining of carcinoma tissue and through use of an ELISA to measure FAS levels in the serum of the patients." (PMID 24527066, 2014). "Numerous studies investigated the role of FAS and FASL gene polymorphisms in the etiology of various cancers including cervix, breast, bladder, lung, prostate, head and neck and esophagus." (PMID 23326385, 2013). "Considering the important role of FAS-1377 G/A SNP in carcinogenesis, we studied all currently eligible case-control studies that included characteristics such as ethnicity, cancer type, smoking behaviors, sex, and control sources." (PMID 24014103, 2013). "Various correlations have been drawn from genetic polymorphisms in the death pathway genes FAS and FASL and the risk of cancer development." (PMID 23326385, 2013). "Other studies have shown its anti-cancer effect, it seems that the RV inhibits tumorogenesis through the induction of apoptosis and the activation of genes FAS, p-53 and p21." (PMID 22289566, 2012). "There are reports regarding upregulation of FAS protein in cancer cells by various plant polyphenols, including EGCG, theaflavins, curcumin, and resveratrol." (PMID 23285096, 2012). "F10 has been reported to activate extrinsic, FAS-mediated apoptosis in other cancer models." (PMID 41303616, 2025). "Additionally, cancer cells can downregulate FAS expression or alter the FAS gene, impairing its function." (PMID 41188939, 2025). "Similarly, enhancing FAS S-acylation to stabilize its membrane clustering and death signal transduction can result in the activation of FAS and potentiate receptor-mediated cancer treatment." (PMID 40304073, 2025). "The EGF/EGFR signaling pathway may play a role in regulating FAS-mediated apoptosis in cancer cells." (PMID 41188939, 2025). "In cancer, PEDF can directly induce apoptosis in cancer cells by upregulating pro-apoptotic factors, primarily through the FAS/FASL pathway, while also downregulating antiapoptotic proteins like the B-cell lymphoma 2 (BCL2) family of proteins, which are associated with the intrinsic pathway." (PMID 39457573, 2024). "A previous study demonstrated that anticancer drugs could sensitize cancer cells to FAS-mediated cytotoxicity." (PMID 39068622, 2024). "In addition, compound 4 is one of the main active components of A. truncatum leaves, which plays a key role in the FAS inhibitory activity and the growth inhibitory activity of various cancer cells." (PMID 37007019, 2023). "However, studies in other cancers profiling the shore regions of the promoter CGI have identified variant methylation at CpG sites, which were negatively correlated with FAS expression." (PMID 37569529, 2023). "Low cell surface expression of FAS may allow cancer cells to more easily bypass the checkpoint in the lungs where FASL is highly expressed." (PMID 37569529, 2023). "GSVA pathway analysis revealed differentially regulated cancer pathways between the three m5C-clusters, including KRAS-related pathways (MAPK-, mTOR-, EGF- and ERK-pathways), cell death pathways (TNFR1-, FAS- and death-pathways), and cancer-related pathways (Wnt-, Gleevec-, MET and CREB-pathways)." (PMID 36060802, 2022). "Furthermore, cytotoxic T cells express FASLG (Fas ligand, CD178), thereby inducing cancer cell apoptosis through its binding with FAS (Fas cell surface death receptor, CD95)." (PMID 35392092, 2022). "Additionally, FAS promotes metastatic spread in pancreatic ductal adenocarcinoma and maintains cancer stemness." (PMID 35249111, 2022). "However, baseline FAS signaling seems crucial for cancer cell survival, since a complete elimination of CD95/CD95L interplay leads to an irreversible cell death called DICE (death induced by CD95R/L elimination)." (PMID 35059842, 2022).
cancer (continued). "Moreover, vitamin C apoptosis induction has been demonstrated via different mechanisms, including activation of NK cells, increased FAS-induced apoptosis via effector T cells, or increased mitochondrial permeability, leading to cancer cell death." (PMID 35798765, 2022). "Therefore, a low baseline level of FAS/FASLG signaling is necessary for the survival of cancer cells." (PMID 35249111, 2022). "Since FAS signaling pathway was commonly impaired in chemoresistant cancers, using ASA combined with Dox might empower the treatment efficacy." (PMID 34319045, 2021). "FAS also plays a critical role in the immune-related elimination of cancer cells." (PMID 33819921, 2021). "Due to FASLG/FAS signaling could induce apoptosis commonly in various cancers, the FASLG is summarized as a tumor suppressor." (PMID 34889164, 2021). "Notably, FAS is an apoptosis-inducing protein and an established target of miR-21, known to be upregulated post-radiation in several types of cancer with a critical role in radiation-induced cell death." (PMID 33672628, 2021). "Accumulated evidence has indicated that FAS plays a key role in cancer progression." (PMID 32963220, 2020). "Various cancer-related pathways emerged to be altered in MM such as integrin signaling pathway, apoptosis signaling pathway, P-53 pathway, Wnt signaling pathway and FAS signaling pathway." (PMID 33585190, 2020). "Further, EV-associated FAS-L purified from patient ascites triggers FAS-induced apoptosis in a T cell line, highlighting the possibility of elimination of FAS-bearing immune cells including T cells by vesicle-delivered FAS-L, a process that allows immune evasion to support cancer cell survival." (PMID 28929459, 2018). "The k-core factor was then applied to identify key regulatory genes, which likely play pivotal roles in gene interactions and regulation, including for key cancer genes, such as p21, FAS, CCND1, and CDK2; real-time PCR confirmed these genes after knockdown of HOXC-AS3." (PMID 30286788, 2018). "Several reports have demonstrated that FAS is involved in cell apoptosis in human cancer." (PMID 29563856, 2018). "Recently, FAS and FASLG polymorphisms have been reported in various cancers and alopecia." (PMID 29950587, 2018). "It was recently shown that activation of GPR30 by E2 increases FAS gene expression in cancer cells." (PMID 27698362, 2016). "Mutations in TRAIL receptors have also been detected in cancers, although not as numerous as for FAS." (PMID 27843441, 2016). "Most of the studies suggested that decreased FAS gene expression and/or increased FASL gene expression is a common feature of malignant transformation and an early event associated with the development of human cancers." (PMID 26858129, 2016). "furthermore, others have reported that cancer cell derived exosomes can create an immunosuppressive microenvironment via induction of T-cell apoptosis and this was imparted via induction of adenosine as well as FAS-FASL ligation." (PMID 26840259, 2016). "Thus, our results challenge earlier proposals that the overexpression of FAS is most intense in carcinomas that carry higher risks." (PMID 26868906, 2016). "FAS expression was frequently observed in carcinomas from the older age group (≥51 years old)." (PMID 24527066, 2014). "In other words, individuals carrying both FAS -1377(GG+GA) and FASL -844(TT+TC) genotypes could be at lower risk for developing cancer than those carrying either FAS-1377(GG+GA) alone, which was consistent with our results." (PMID 24014103, 2013). "Given the critical roles of FAS and FASL in the apoptotic process, it is biologically plausible that an alteration in either of these factors via a genetic polymorphism may affect cancer risk." (PMID 24014103, 2013).